XRCC3 (X-ray repair cross complementing 3)
Diseases named in the same sentence as XRCC3 in open-access papers (continued):
Sharing a sentence is not in itself a finding about the gene and the disease.
breast cancer (continued). "We screened the RAD51, XRCC3, and XRCC2 genes for germline variation in familial BRCA1/2-negative breast or ovarian cancer patients in order to evaluate the role of these genes in breast cancer predisposition in Finland and to identify putative recurrent founder mutations." (PMID 25918678, 2015). "This is the first report that provides experimental results showing that a DNA repair protein is involved in the regulation of invasiveness and tumour growth in human breast cancer cells and suggests that XRCC3 expression could be used as a biomarker for breast tumour growth and development." (PMID 21283680, 2011). "In this study, we used clinical specimens and confirmed the role of XRCC3 and RAD51 in development and progress of breast cancer." (PMID 23977219, 2013). "In this study, immunohistochemistry was used to explore the prevalence of XRCC3 and RAD51 expression and their possible roles in breast cancer." (PMID 23977219, 2013). "Our results showed that the expression levels of both XRCC3 and RAD51 were significantly increased in breast cancer, which was consistent with their high mRNA expressions." (PMID 23977219, 2013). "Data showed that expressions for both XRCC3 and RAD51 were significantly increased in breast cancer." (PMID 23977219, 2013). "We assessed the effect of the DNA repair proteins known as X-ray complementing protein 3 (XRCC3) and RAD51, to the invasive behavior of the MCF-7 luminal epithelial-like and BT20 basal-like triple negative human breast cancer cell lines." (PMID 21283680, 2011). "Some SNPs also showed a significant effect on survival outcomes, such as RAD51-135 G>C in breast cancer, XRCC2 R188H in pancreatic cancer, and SNPs of RAD51-135 G>C and XRCC3 T241M in acute myeloid leukemia." (PMID 21647442, 2011). "Moreover, the knockdown of RAD51, BRCA1 (breast cancer 1), and the RAD51 paralog XRCC3 (X-ray repair cross complementing 3) prevented the repair of the O6mG-induced DSBs leading to cell sensitization, while RAD51-CRISPR activation led to TMZ resistance." (PMID 35626024, 2022). "The absence of mutations in our study as well as the results of the previous studies indicates that XRCC3 and RAD51 are not major breast cancer susceptibility genes." (PMID 25918678, 2015). "Our results suggest that RAD51, XRCC3, and XRCC2 do not substantially contribute to breast cancer predisposition in the Finnish population." (PMID 25918678, 2015). "Base on these results, we are disposed to agree that overexpression of XRCC3 and RAD51 may play an important role in the pathogenesis of breast cancer." (PMID 23977219, 2013). "The mean percentage of positive cells was much higher in breast cancers than in adjacent non-cancerous tissues (XRCC3: 64% vs. 20%; RAD51: 83% vs. 55%)." (PMID 23977219, 2013). "As the roles of XRCC3 and RAD51 on cellular invasiveness are unknown, we explored the phenotypic effect resulting in the over-expression of XRCC3 and RAD51 on different breast cancer cell lines, vis-^-vis invasiveness." (PMID 21283680, 2011). "In conclusion, the absence of mutations among breast cancer families and similar distribution of haplotypes between breast cancer cases and controls suggests that RAD51, XRCC3, and XRCC2 do not substantially contribute to familial breast cancer predisposition in the Finnish population." (PMID 25918678, 2015). "But the expression of XRCC3 in breast cancer was not well studied." (PMID 23977219, 2013). "Immunohistochemistry was used to detect protein expressions of XRCC3 and RAD51 in 248 cases of breast cancer tissue and 78 cases of adjacent non-cancerous tissue." (PMID 23977219, 2013). "Expression of XRCC3 and RAD51 in breast cancer and adjacent non-cancerous tissue." (PMID 23977219, 2013).
lung carcinoma (20 papers, 2007 to 2025). "In conclusion, this meta-analysis indicates that XRCC1 −77T>C shows an increased lung cancer risk and XRCC3 T241M polymorphism is associated with decreased lung cancer risk, especially in Caucasians." (PMID 23990873, 2013). "In order to explore the association between XRCC1 Arg399Gln, Arg194Trp, Arg280His, −77T>C, and XRCC3 T241M polymorphisms with lung cancer risk, a meta-analysis was conducted to summarize the data." (PMID 23990873, 2013). "Third, our meta-analysis explores and analyzes the sources of heterogeneity between studies about XRCC3 T241M and Arg280His in lung cancer risk." (PMID 23990873, 2013). "Taken together, our study significantly demonstrated an independent and synergistic contribution of XRCC1 gene Arg399Gln and XRCC3 gene Thr241Met polymorphisms to lung cancer susceptibility in northeastern Chinese." (PMID 23409158, 2013). "Recently, many studies have investigated the role of the XRCC3 Thr241Met gene polymorphism in lung cancer." (PMID 23289442, 2013). "In this study, we sought to investigate the association of three well-characterized nonsynonymous polymorphisms in XRCC1 and XRCC3 genes with lung cancer in northeastern Chinese." (PMID 23409158, 2013). "By far, several meta-analyses have summarized the predisposition of XRCC1 and XRCC3 genetic polymorphisms to lung cancer." (PMID 23409158, 2013). "Molecular epidemiological studies have reported the association of XRCC1 Arg399Gln, Arg194Trp, Arg280His, −77T>C, and XRCC3 T241M with lung cancer risk, but the results remain conflicting rather than conclusive." (PMID 23990873, 2013). "In conclusion, this meta-analysis indicates that XRCC1 −77T>C shows an increased lung cancer risk and XRCC3 T241M polymorphism is associated with decreased lung cancer risk in Caucasians." (PMID 23990873, 2013). "As a result, the significant association was found between the XRCC3 Thr241Met polymorphisms and colorectal and lung cancer, more importantly, the risk of lung cancer of XRCC3 Thr241Met polymorphisms was relatively high (OR = 2.52, 95%: 1.44-4.41)." (PMID 23289442, 2013). "Although several studies previously performed pooling analyses regarding the association of XRCC1 Arg399Gln, Arg194Trp, Arg280His, −77T>C, and XRCC3 T241M with lung cancer risk." (PMID 23990873, 2013). "The previous studies also point out to the relation of XRCC1 (Arg399Gln, Arg194Trp) and XRCC3 Trp241Met polymorphisms with colorectal cancer, skin cancer, lung cancer, and others." (PMID 23675381, 2013). "Many studies have examined the association between the XRCC3 Thr241Met gene polymorphism and lung cancer risk in various populations, but their results have been inconsistent." (PMID 23289442, 2013). "Many molecular epidemiological studies have reported the role of XRCC1 Arg399Gln, Arg194Trp, Arg280His, −77T>C, and XRCC3 T241M in lung cancer risk, but the results remain conflicting rather than conclusive." (PMID 23990873, 2013). "Present meta-analysis results were not consistent with a previous meta-analysis on XRCC1 and XRCC3 polymorphisms with lung cancer risk." (PMID 23990873, 2013). "Three out of 17 studies examined the association of XRCC3 Thr241Met genotype and the risk of different histological types of lung cancer including SCC and AC." (PMID 23289442, 2013). "To unravel its genetic underpinnings, we sought to investigate the association of three well-characterized nonsynonymous polymorphisms in XRCC1 (Arg194Trp and Arg399Gln) and XRCC3 (Thr241Met) genes with lung cancer risk in northeastern Chinese." (PMID 23409158, 2013). "We investigated the relationship between polymorphisms in two NER genes, XPC (poly (AT) insertion/deletion: PAT-/+) and XPD (Asp312Asn and Lys751Gln), the BER gene XRCC1 (Arg399Gln), and the DSBR gene XRCC3 (Thr241Met) and the risk of developing lung cancer." (PMID 17705814, 2007).
lung carcinoma (continued). "In conclusion, we analysed the association between XPC, XPD, XRCC1, and XRCC3 polymorphisms and the individual susceptibility to develop lung cancer in the Spanish population, specifically with a highly tobacco exposed population." (PMID 17705814, 2007). "In particular, it has been reported in a meta-analysis that XRCC3 316A>G Thr241Met (rs1799794) is related with response to platinating agents, which highlights the prognostic value of XRCC3 Thr241Met polymorphism in patients with lung cancer." (PMID 29163177, 2017). "Several study demonstrated that XRCC3 polymorphisms are implicated in breast cancer, lung cancer." (PMID 25247297, 2014). "In addition, the sample size was also too small for the XRCC3 Thr241Met polymorphism and lung cancer risk in Asians and Africans." (PMID 23990873, 2013). "Therefore, genotyping data from XRCC1 and XRCC3 genes, incorporating the haplotype and synergism analytical strategies would facilitate the identification of individuals at high risk of developing lung cancer in future clinical screening." (PMID 23409158, 2013). "However, in further subgroup and sensitivity analyses, we found XRCC3 T241M polymorphism was associated with lung cancer risk in Caucasians." (PMID 23990873, 2013). "Many studies have reported the association of X-ray repair cross-complementing group 1 (XRCC1) Arg399Gln, Arg194Trp, Arg280His, −77T>C, and X-ray repair cross-complementing group 3 (XRCC3) T241M polymorphisms with lung cancer risk, but the results remained controversial." (PMID 23990873, 2013). "Results of meta-analysis for XRCC1 and XRCC3 polymorphisms and lung cancer risk." (PMID 23990873, 2013). "However, a study with a larger sample size is needed to further evaluate gene-environment interaction on XRCC1 Arg399Gln, Arg194Trp, Arg280His, −77T>C, and XRCC3 T241M polymorphisms and lung cancer risk." (PMID 23990873, 2013). "In this study, we assessed the OGG1 Ser326Cys, MUTYH Gln324His, APEX1 Asp148Glu, XRCC1 Arg399Gln, and XRCC3 Thr241Met gene polymorphisms that may influence DNA repair capacity and their association with the overall survival of lung cancer patients." (PMID 23443124, 2012). "Since the identification of XRCC3 Thr241Met polymorphism, a growing number of studies suggested that XRCC3 Thr241Met polymorphism plays an important role in the development of cancers, such as glioma, hepatocellular carcinoma, head and neck cancer, lung cancer, and so on." (PMID 24254304, 2014). "Furthermore, despite the fact that the polymorphism in XRCC3 didn't alter the overall risk of developing lung cancer when studied independently, when this polymorphism was combined with those studied in XPC or XPD, we observed an interaction between these polymorphisms." (PMID 17705814, 2007). "In lung cancer, SNPs in genes such as XPD and XRCC3 have been consistently implicated as key predictors of therapeutic response and prognosis." (PMID 40833230, 2025). "In this study, we also investigated the correlations between 35 polymorphisms in 9 DNA repair genes (XRCC3, BRCA2/ZAR1L, XPC, RAD52, MAD2L2, NFKB1, NFKBIA, TNFRSF1A, and FASN) with platinum-based chemotherapy prognosis in 399 patients with lung cancer." (PMID 35899106, 2022). "XRCC3 IVS6 C1571T and the associated haplotype AAC are associated with a relatively high risk of lung cancer." (PMID 34486486, 2021). "After knockdown of HPV16 E6 in HPV-positive lung cancer TL-1 cells, the expression of XRCC3 and XRCC5 genes was increased in response to the B[a]P treatment compared with their parental cells." (PMID 26918347, 2016). "For practical reasons, we hope that this study will establish background data for further investigations into the mechanisms of XRCC1 and XRCC3 genes and the development of lung cancer." (PMID 23409158, 2013). "The principal finding was XRCC1 gene Arg399Gln and XRCC3 gene Thr241Met per se were significant contributors to lung cancer." (PMID 23409158, 2013).
lung carcinoma (continued). "We focused on OGG1 Ser326Cys, MUTYH Gln324His, APEX1 Asp148Glu, XRCC1 Arg399Gln, and XRCC3 Thr241Met and examined the relationship between the different genotypes and survival of Japanese lung cancer patients." (PMID 23443124, 2012). "Thus, XRCC3, XRCC5, DNA adduct levels, and HPV 16 E6 oncoprotein levels were contributors to EGFR gene mutation in lung cancer patients." (PMID 26918347, 2016). "There were only small number of studies examined the association between the XRCC3 Thr241Met gene polymorphism and lung cancer risk in smokers or non-smokers; moreover, the p value of Q test for heterogeneity test was significant." (PMID 23289442, 2013). "In further stratified and sensitivity analyses, significantly decreased lung cancer risk was observed in Caucasians for XRCC3 T241M, but not in Asians." (PMID 23990873, 2013). "Our meta-analysis results showed no significantly risks were found to be associated with the XRCC3 Thr241Met polymorphisms and lung cancer risk in smokers or non-smokers." (PMID 23289442, 2013). "Our study significantly demonstrated an independent and synergistic contribution of XRCC1 Arg399Gln and XRCC3 Thr241Met polymorphisms to lung cancer susceptibility in northeastern Chinese." (PMID 23409158, 2013). "Previous studies found some potentially functional SNPs of HR genetic polymorphisms (e.g., RAD51-135 G>C, −172G>T, XRCC2 4234G>C, R188H, XRCC3 T241M and NBN E185Q) to be associated with various types of cancer risks, including cancers of the lung, breast, ovary, leukemia and head and neck." (PMID 21647442, 2011). "Individuals with the XPC PAT(+/+)/XRCC3 241Met/Met or XPD 751Gln/Gln/XRCC3 241Met/Met genotypes showed a not significant higher risk of developing lung cancer 3.06 (CI = 0.91–10.30) (P = 0.071) and 2.66 (CI = 0.74–9.62) (P = 0.135) respectively." (PMID 17705814, 2007). "We have determined the frequency of 5 polymorphisms in 4 different genes implicated in DNA damage repair (XPC PAT, XPD Asp312Asn, XPD Lys751Gln, XRCC1 Arg399Gln, and XRCC3 Thr241Met) in lung cancer patients and matched controls in order to evaluate their association with the risk of lung cancer." (PMID 17705814, 2007). "In this study, we sought to investigate the association of three well-characterized nonsynonymous polymorphisms in XRCC1 (rs1799782∶Arg194Trp and rs25487∶Arg399Gln) and XRCC3 (rs861539∶Thr241Met) genes with risk of lung cancer in a northeastern Chinese population." (PMID 23409158, 2013). "In the process of histological differentiation of lung cancer, XRCC3 Thr241Met polymorphisms may be not independent factor." (PMID 23289442, 2013). "In the HPV-positive lung cancer cells, after knockdown HPV16 E6 expression, the promoter hypermethylation of the XRCC3 and XRCC5 genes was decreased." (PMID 26918347, 2016). "Gene and protein expression of two DNA repair genes, XRCC3 and XRCC5, were lower in B[a]P-treated E6-positive cells than in E6-negative lung cancer cells." (PMID 26918347, 2016). "Finally, in order to test whether individual polymorphisms in DNA repair genes might interact and modify the risk of developing lung cancer, ORs were estimated for each pair of the studied polymorphisms (XPC PAT, XPD Asp312Asn, XPD Lys751Gln, XRCC1 Arg399Gln and XRCC3 Thr241Met)." (PMID 17705814, 2007). "However, it has also been shown that the common and the variant XRCC3 alleles are functionally equivalent in the double-strand break repair pathway, which may explain the lack of association between XRCC3 Thr241Met polymorphism and lung cancer risk shown in several studies." (PMID 17705814, 2007).
lung carcinoma (continued). "The protein expression of hMLH1, hMSH2, XRCC1, XRCC3, XRCC5, BRCA1, and BRCA2 repair genes in B[a]P-treated HPV-positive and -negative lung cancer cells was analyzed by western blotting." (PMID 26918347, 2016).
ovarian carcinoma (16 papers, 2013 to 2024). A malignant neoplasm originating from the surface ovarian epithelium. "The effects and underlying mechanism of XRCC3 rs861539 on the risk of ovarian cancer (OC) are still unclear." (PMID 37212185, 2023). "In the subgroup analysis based on ethnicity, we found that XRCC3 rs861539 was associated with ovarian cancer risk in Caucasians." (PMID 35978646, 2022). "A number of studies have reported an association between XRCC3 rs861539 polymorphism and ovarian cancer risk." (PMID 35978646, 2022). "Current studies on the relationship between XRCC3 rs861539 polymorphism and ovarian cancer risk have been inconsistent." (PMID 35978646, 2022). "This meta-analysis showed a significant association between XRCC3 rs861539 polymorphism and ovarian cancer risk, especially in Caucasians." (PMID 35978646, 2022). "Although many studies have explored the association between XRCC3 rs861539 polymorphism and ovarian cancer risk, the conclusions have been inconsistent." (PMID 35978646, 2022). "For the overall data, the current meta-analysis showed an association between XRCC3 rs861539 polymorphism and ovarian cancer risk in the heterozygote model and the dominant model." (PMID 35978646, 2022). "In this meta-analysis, two genetic models produced statistically significant in the estimation of correlation between XRCC3 rs861539 polymorphism and ovarian cancer risk." (PMID 35978646, 2022). "This study demonstrated that XRCC3-Met/Met genotype of Thr241Met polymorphism was statistically significantly correlated with ovarian cancer." (PMID 30712190, 2019). "The presented study demonstrated a significant association of studied Thr241Met polymorphism of XRCC3 gene with the occurrence of ovarian cancer." (PMID 30712190, 2019). "A likely deleterious missense mutation in the XRCC3 gene has been identified in one breast and ovarian cancer family." (PMID 25918678, 2015). "In conclusion, this meta-analysis shows that the XRCC3 were associated with ovarian cancer risk overall for Caucasians." (PMID 25006581, 2014). "To summarize the effect of the XRCC3 polymorphism on the risk for ovarian cancer, we performed a meta-analysis." (PMID 25006581, 2014). "For XRCC3 rs1799796 polymorphisms, we also observed a statistically significant correlation with ovarian cancer risk using the heterozygote comparison (T1T2 versus T1T1: OR = 0.91, 95% CI = 0.83–0.99, P = 0.04)." (PMID 25006581, 2014). "So further studies should be done to explore the possible relationships between XRCC3 polymorphisms and ovarian cancer risk in other ethnicities." (PMID 25006581, 2014). "The association between XRCC3 polymorphism and ovarian cancer has been studied; however, those experimental results remain confusing." (PMID 25006581, 2014). "In summary, our meta-analysis systematically analyzed the association between XRCC3 Thr241Met polymorphism and the risk of ovarian cancer." (PMID 24254304, 2014). "Previous studies were performed to investigate the relationship between the XRCC3-18067C/T polymorphism and ovarian cancer risk." (PMID 24254304, 2014). "Genetic polymorphism of X-ray repair crosscomplementing group 3 (XRCC3) Thr241Met has been implicated to alter the risk of ovarian cancer, but the results are controversial." (PMID 24254304, 2014). "The association between the XRCC3 Thr241Met polymorphism and ovarian cancer risk was conducted by odds ratios (ORs) and 95 % confidence intervals (95 % CIs)." (PMID 24254304, 2014). "It was reported that the XRCC3 polymorphism increased the risk of many cancers, including ovarian cancer." (PMID 25006581, 2014). "Many published studies that aim at the role of XRCC3 Thr241Met polymorphism in ovarian cancer risk have been performed, but the results are controversial." (PMID 24254304, 2014). "To assess the association between XRCC3-18067C/T polymorphism and ovarian cancer risk more precisely, we conducted a meta-analysis." (PMID 24254304, 2014).